EGFR (epidermal growth factor receptor)
Diseases named in the same sentence as EGFR in open-access papers (continued):
Sharing a sentence is not in itself a finding about the gene and the disease.
cancer (continued). "In patients treated with PD-1/PD-L1 inhibitors, the survival rates of patients with EGFR wild-type and rare mutant carcinomas were higher than those with L858R and exon 19 deletion carcinomas." (PMID 37033978, 2023). "Treatment of carcinomas with cisplatin has also been shown to induce nuclear translocation of EGFR and increase resistance to chemotherapy." (PMID 36982894, 2023). "The epidermal growth factor receptor (EGFR) is a tyrosine kinase receptor which is commonly upregulated in several types of carcinoma." (PMID 37240168, 2023). "Compared to EGFR mutants, EGFR wild-type carcinomas had higher numbers of CD8+ T cells, CD4 memory activated T cells and neutrophils, and lower numbers of resting dendritic cells and resting mast cells, in two of the datasets." (PMID 37033978, 2023). "Thereafter, the partially active EGFR phosphorylates CaM, which further enhances its activity, in agreement with our findings in human carcinoma epidermoid A431 cells." (PMID 36979639, 2023). "In invasive squamous cell carcinoma of the head and neck region, 80% of carcinomas have an overexpression of EGFR." (PMID 37370810, 2023). "Epidermal growth factor receptor (EGFR) is a notable receptor tyrosine kinase and proto-oncogene complicit in the pathogenesis of numerous carcinomas, with EGFR expression found to increase throughout prostate carcinogenesis." (PMID 37191417, 2023). "In CRC pathogenesis, the EGFR signaling pathway is related to promoting cancer cell proliferation, migration, apoptosis inhibition, angiogenesis, and immune evasion." (PMID 36005485, 2022). "This study advances our mechanistic understanding of how allosteric and ATP-competitive EGFR inhibitors synergize to target EGFR-driven cancers and provides insight to guide the future development of combination therapies." (PMID 35534503, 2022). "A real-time peptide nucleic acid (PNA)-mediated polymerase chain clamping assay was used to detect the T790M EGFR mutation on both BALF and bronchial biopsy specimens of cancer-afflicted persons." (PMID 36552956, 2022). "Epidermal growth factor receptor (EGFR) is a transmembrane protein with cytoplasmic kinase activity commonly overexpressed in various human cancers, including NSCLC." (PMID 35721193, 2022). "Overall statistical support for sensitivity associations with SBS36/56L and SBS18/36L was higher for the EGFR-targeting drugs than for all other classes of drugs in these cancer types." (PMID 35614096, 2022). "Most importantly, EGCG administration inhibited the phosphorylation of EGFR, making the cancer cells more sensitive to Gefitinib." (PMID 36545470, 2022). "EGFR is a membrane receptor of the tyrosine kinase family mainly controlling cell proliferation and development, thus being involved in cancer pathogenesis, but also regulating apoptosis, oxidative status, and metabolism." (PMID 36430946, 2022). "It selectively infects cancer cells and replicates due to active RAS signaling pathway, K-Ras, BRAF, and EGFR mutations in cancer cells." (PMID 35686109, 2022). "EGFR is a member of the ErbB family of receptor tyrosine kinases that play an important role in the pathogenesis of human cancers." (PMID 35160746, 2022). "Incubation of cancer cells with the free ligand EGF also reduced B-ASO binding (by competition) with the extracellular domain of EGFR, reaching boron cellular uptake levels of 14 and 8 μg B/g for A431 and U87 cell lines, respectively." (PMID 36499115, 2022). "Accordingly, recent data have shown that curcumin, a polyphenol extracted from Curcuma longa, affects the EGFR tyrosine kinase autophosphorylation and induces the EGFR downregulation in a dose- and time-dependent manner in different types of cancer cells." (PMID 36428610, 2022). "Although, gefitinib is effective in EGFR-expressing cancer cells but provokes innate resistance via nuclear factor-kappa B (NF-κB) signaling." (PMID 35578244, 2022).
cancer (continued). "CaCCinh-A01 also inhibits the growth of HNSCC cells by reducing EGFR activity and sensitises the cancer cells to EGFR-targeted therapy." (PMID 36497413, 2022). "Clinically approved inhibitors of EGFR signaling, acquired resistance mechanisms, clinical efficacy, and safety profile identified in patients with cancer." (PMID 36185288, 2022). "Vaccinia virus (VV) targets cancer cells that overexpress EGFR as it requires EGFR-Ras signaling to replicate." (PMID 36221123, 2022). "Several data have demonstrated the relationship between G-protein-coupled receptors (GPCRs) and EGFR via transactivation in different cancers." (PMID 35565451, 2022). "It has been reported that EGFR mutation is involved in the RANKL pathway and EGF signals are involved in bone metastasis of many cancers." (PMID 36581856, 2022). "G protein coupled receptors (GPCRs), Integrins, sigma receptors, Epidermal growth factor receptor, Sigma receptors (SRs) these over expressed receptors are frequently used in preclinical cancer models for selective drug delivery via receptor–ligand pairs." (PMID 36688039, 2022). "The discovery of EGFR-activating mutations in NSCLC and the success story of EGFR tyrosine kinase inhibitors (TKIs) have shifted the paradigm of cancer therapy from cytotoxic chemotherapy to targeted therapies." (PMID 35056800, 2022). "This suggests that let-7-free GE11 exosomes are a potential tool for delivering drugs to EGFR-expressing cancers such as BRC." (PMID 35663957, 2022). "Structure 104 was evaluated for its inhibitory effect against three cancer targets: tubulin, EGFR, and BRAF." (PMID 36558921, 2022). "Overall, these results indicated that PM-stimulated macrophages showed increased expression of HBEGF, which stimulated EGFR on cancer cells and increased their motility." (PMID 36352257, 2022). "Conventional scFv-based EGFR-redirected CAR-Ts have been investigated for targeting various types of cancers." (PMID 35468841, 2022). "The epidermal growth factor receptor (EGFR) plays an important role in human tumors, by regulating cancer cell proliferation and survival." (PMID 35406622, 2022). "Due to its action, gefitinib has been used in the treatment of cancers that present abnormally increased expression of EGFR." (PMID 35216325, 2022). "Recent studies have reported synergistic effects of nutritional supplementation with FO and Se on apoptosis and reduced resistance to EGFR inhibitors in some cancer cells 12,13." (PMID 36483592, 2022). "In our model, the bulk of cytokines and their receptors are expressed in CD45+ cells with few from EGFR+ cancer cells." (PMID 35624211, 2022). "More novel cancer therapeutics, such as targeted therapies [e.g., epidermal growth factor receptor (EGFR) inhibitors and tyrosine kinase inhibitors (TKI)] and emerging immunotherapies, have also demonstrated oral side effects." (PMID 35548170, 2022). "Complexes were constructed from ionizable cationic amino lipids coated with anti-EGFR antibodies, providing cancer-specific uptake." (PMID 35008996, 2022). "EGFR activates a variety of effector pathways in cells, and thus we wanted to explore which effector pathway NNMT-EGFR activates to exert its cancer-promoting effect." (PMID 35851575, 2022). "The common mechanism involved in cancer is dysregulation of the EGFR that plays a vital role in cell survival, growth, differentiation, and tumorigenesis." (PMID 35421091, 2022). "The over-expression of EGFR in tumors is an excellent target for the development of cancer imaging agents." (PMID 35120180, 2022). "We selected 17 human cancer cell lines with known mutant genes, such as EGFR, VEGF, BRAF, ALK, and HER2." (PMID 36313330, 2022). "EGFR has emerged as an oncogenic driver in a subset of patients with NSCLC, while widespread overexpression of EGFR protein has been found in a broad range of different types of cancer." (PMID 36185288, 2022).
cancer (continued). "Knowledge of the role of the EGFR in malignant tumors has advanced enormously over the last 20 years, and several therapeutic drugs such as tyrosine kinase inhibitors and anti-EGFR monoclonal antibodies have been registered for epithelial-derived tumors." (PMID 35306855, 2022). "Resveratrol, as a polyphenol, has been shown to exert inhibitory activity against many cancer types, especially through the mechanism of targeting deregulated EGFR signaling pathway in cancer cells." (PMID 35269825, 2022). "The convergence between Wnt/β-catenin and EGFR signaling in cancers has previously been thoroughly reviewed." (PMID 35744950, 2022). "This review aims to understand how lysosomal changes can affect EGFR-mediated cancers and suggest a new approach to developing cancer therapies targeting lysosomes and EGFR." (PMID 36438839, 2022). "A greater number of NSCLC patients will have data regarding their cancer’s genomic details as EGFR TKIs become more widely accepted for adjuvant and potentially neoadjuvant therapy, which will also enable greater sample sizes and confidence in results." (PMID 36661661, 2022). "Shorter peptides were also conjugated to AuNP—photosensitizer adducts to target EGFR-overexpressing cancer cells." (PMID 35213974, 2022). "Another modality, based on the CAR-T cells against molecular targets on the cancer cell surface, such as epidermal growth factor receptor (EGFR), and CD133 is still under assessment." (PMID 35743107, 2022). "Studies show that F2R can influence platelet mobilization as well as epidermal growth factor receptor signaling pathways to promote cancer progression." (PMID 35186111, 2022). "To summarize, these findings suggest that altered glycosylation of several distinct metastasis-associated glycoproteins, including integrins, EGFR, and MMP-14, is a key to the highly invasive cancer cell phenotype." (PMID 35028012, 2022). "We select and focus on EGFR and TGFβR here to illustrate how growth factors regulate cancer cell proliferation and migration through redox cycling." (PMID 36551308, 2022). "Extensive research has focused on the effects of curcumin and its analogs targeting EGFR in cancer cells." (PMID 35977996, 2022). "The internalization of EGFR is differentially regulated by its ligands and several mechanisms that contribute to cancer development." (PMID 35681787, 2022). "EGFR promotes metabolic processes critical for cancer cell proliferation both directly by phosphorylating rate‐limiting enzymes or indirectly through the activation of the MYC transcription factor and of the AKT signaling cascade." (PMID 35814444, 2022). "Epidermal growth factor receptor (EGFR) has been one of the most effective oncogenes that are usually altered in cancers." (PMID 35203275, 2022). "In other words, cancer evolution upon EGFR blockade must have occurred also in those patients in whom radiological determination did not highlight a clinical response." (PMID 35915157, 2022). "The results have shown that this herbal extract significantly reduces cancer cell proliferation and migration, induces cancer cell apoptosis, and decreases the expression of EGFR in vitro." (PMID 34882994, 2022). "Cetuximab, a recombinant chimeric mAb with a murine variable region and a human constant region that has been successfully used to treat cancer by targeting the epidermal growth factor receptor." (PMID 36688039, 2022). "As such, several affibody molecules have been extensively investigated as scaffolds for direct cancer imaging and treatment, including EGFR." (PMID 35213974, 2022). "Current active targeting strategies mainly target growth factor receptors overexpressed in cancers of different tissue origins, such as folate (FA), transferrin (Tf) receptor, epidermal growth factor receptor (EGFR) and so on." (PMID 36421144, 2022).
cancer (continued). "Both drugs are FDA approved and are typically used as anti-cancer therapies, with Lapatinib targeting epidermal growth factor receptor (EGFR) and Carfilzomib targeting the proteasome." (PMID 35316308, 2022). "For comparison, two FDA-approved antibodies, Cetuximab, a monoclonal antibody against EGFR for treatment of various cancers, has a Kd of 0.38 nM, and Trastuzumab (i.e., herceptin), a recombinant antibody against HER2, has a Kd of ~5–9 nM." (PMID 36559106, 2022). "A growing body of evidence demonstrates that unique weapons for selective ablation of cancer cells can be generated via the engineering of bona-fide EGFR-targeting moieties with light-activable PDT sensitizers or nanoparticles." (PMID 35213974, 2022). "These identified unique features should be considered when designing combinatorial treatment regimens for EGFR WT cancer patients." (PMID 36230688, 2022). "This review will summarise the role of EGFR in cancer cell biology and the current challenges with EGFR-targeted therapy." (PMID 36497413, 2022). "As an illustration, some cancer detection protocols carried out by anti-EGFR-covered gold nanoparticles (NPs) of 20 nm exhibited strong cancer uptake." (PMID 36362293, 2022). "The overexpression of EGFR plays an important role in the progression of malignant tumours, such as glioblastoma, head and neck cancer, NSCLC, pancreatic cancer, breast cancer, and so on." (PMID 35589670, 2022). "As one of the most clinically useful targets, EGFR has been applied as a gold standard for treating various cancer patients." (PMID 35614042, 2022). "This review discusses EGFR-targeting therapies acting through distinct molecular mechanisms to destroy EGFR-expressing cancer cells." (PMID 36185288, 2022). "A combination regimen using a Src-targeting Saracatinib with lapatinib (targets EGFR and HER2) prevented the growth of disseminated cancer cells by causing cell cycle arrest." (PMID 35327469, 2022). "In GBM patients expressing MUC4, the protein was found in the cytoplasm of cancer cells, in a manner similar to EGFR." (PMID 36400876, 2022). "A similar combinatory approach with EHMT inhibitors can be considered for cancers with aberrant EGFR signaling and EHMT expression." (PMID 35740522, 2022). "Among promising anti-cancer therapeutics, those aimed at the epidermal growth factor receptor (EGFR) family are being extensively developed." (PMID 36432639, 2022). "Previous studies revealed that EGFR is one of the genes mainly regulated by HOXB5 in cancer progression." (PMID 35847904, 2022). "RAS, PI3K, and EGFR, which are involved in both glycolysis pathways and cancer pathway, were significantly upregulated in HSCC." (PMID 36090994, 2022). "That TERTp mutations are necessary for clonal expansion suggests telomere maintenance is also required by pre-cancer cells to overcome replicative senescence after acquiring strong drivers such as EGFR through amplification or copy number gain." (PMID 36130485, 2022). "It has been shown that the dysregulation of the Wnt/β-catenin signaling promotes the occurrence and development of various cancers by regulating the EGFR (epidermal growth factor receptor), Hippo/YAP, and NF-κB (nuclear kappa-B) pathways." (PMID 36276285, 2022). "TKIs reduce downstream signaling and inhibit cancer cell proliferation and survival by inactivating EGFR-mediated signaling." (PMID 36080307, 2022). "Pathway scores for cell proliferation, cell growth factors, cell differentiation, choline cancer metabolism, and carbon cancer metabolism have been shown to correlate with the functional status of EGFR." (PMID 35705962, 2022). "N-cadherin-mediated adherens junctions as the EMT hallmark facilitates the activation of epidermal growth factor receptor/RhoAGTP interaction, and PKCα/ERK pathways are associated with cancer cell motility." (PMID 35804959, 2022). "Drug resistance in advanced cancers is mediated by different factors, such as overexpression of EGFR and DNA repair enzymes." (PMID 35702041, 2022).
cancer (continued). "B-ASO (80 pmol/well) was efficiently taken up from the medium by various cancer cells overexpressing EGFR compared to the normal cells or human macrophages where the uptake was lower since the natural expression level of EGFR is low." (PMID 36499115, 2022). "In the present study, we calculated the binding affinities of 50 curcumin derivatives to known cancer-related target proteins of curcumin, i.e., epidermal growth factor receptor (EGFR) and nuclear factor κB (NF-κB) by using a molecular docking approach." (PMID 35409325, 2022). "(Ra)-2’s mutant selectivity over WT-EGFRcompares favorably to that of osimertinib, the standard of care formutant EGFR cancers, particularly for the L858R/T790M/C797S mutantwhich has proven to be a challenge to the drug." (PMID 36153960, 2022). "Overexpression of epidermal growth factor receptor (EGFR) has been used in other cancers as an imaging biomarker to identify cancerous tissue." (PMID 36357495, 2022). "For that reason, we performed WES and identified highly relevant variants in cardiac and cancer genes, such as PRDM16 (p.P878L) in ACT patient 2, and SYNM (p.V1004I), TTN (p.V27642M), and an EGFR (p.E868Nfs*35) variant in ACT-3." (PMID 35260914, 2022). "Published data also suggests that EGFR-mediated calcium signalling is involved in drug resistance in cancer." (PMID 36497413, 2022). "We found that chemical inhibition of EGFR combined with the siRNA-mediated knockdown of STYK1 led to a significant decrease in cancer cell viability and anchorage-independent cell growth." (PMID 35840561, 2022). "Gefitinib and erlotinib are selective EGFR TKIs explaining anticancer action either singly or combined with radiation therapy and chemotherapy in human cancer xenografts." (PMID 35402265, 2022). "In conclusion, our results demonstrated that FGFC1 exhibited anti-cancer effects in EGFR-mutant NSCLC PC9 cells in vitro and in vivo via induction of G0/G1 cell cycle arrest and cell apoptosis mediated by the NF-κB signaling pathway." (PMID 35049931, 2022). "In non-small-cell lung cancer (NSCLC), tyrosine kinase inhibitors that target the epidermal growth factor receptor (EGFR-TKIs) exhibit good efficacy in cancer treatment until acquired resistance occurs." (PMID 35888768, 2022). "The selection of the FDA-approved gefitinib and erlotinib TKIs was based on the reported efficacy of these drugs in chemotherapeutic treatments of cancer patients with EGFR-induced tumors." (PMID 36003330, 2022). "Systemic intraperitoneal injection of LNPs resulted in their accumulation in EGFR-overexpressing cancer cells and resulted in an approximately 82% editing rate of PLK1 and increased survival by around 80%." (PMID 35008996, 2022). "EGFR is not only essential for normal physiological activities, but is also involved as an oncogenic driver in the development and spread of various cancers." (PMID 36499115, 2022). "In a multicenter retrospective clinical cancer study, 171 NSCLC patients with EGFR mutations were treated with PD-1/PD-L1 ICIs or ICIs combined with a CTLA4 inhibitor." (PMID 35935943, 2022). "For all investigated cancer types, the author observed that mutations in upstream components of the MAPK/ERK signaling pathway, namely EGFR and RAS family proteins, co-occur much less frequently than expected with oncogenic mutations in BRAF." (PMID 36275468, 2022). "It has also been reported that alterations of m6A levels of MYC and EGFR are involved in the regulation of cancer pathogenesis and progression." (PMID 35874897, 2022). "It was also noticed that the established EGFR inhibitor gefitinib exhibited relatively low anti-cancer activity across the four UM cells tested, which is consistent with clinical observations." (PMID 35781872, 2022). "Induction of PD-L1 is another important mechanism of PKCδ promoting cancer progress and escaping immune surveillance, which also uncovers a novel pathway between EGFR and PD-L1." (PMID 36482371, 2022).